SOX2 (SRY-box transcription factor 2)
Diseases named in the same sentence as SOX2 in open-access papers (continued):
Sharing a sentence is not in itself a finding about the gene and the disease.
colorectal cancer (continued). "In skin and colorectal cancers, SOX2-expressing tumor cells were found to exhibit more pronounced stemness characteristics and high tumorigenicity." (PMID 37213675, 2023). "In concert with IGF2BP2, METTL3 promotes m6A modification of the SOX2 CDS region to inhibit SOX2 RNA degradation, which increases the protein content of intracellular SOX2 and induces colorectal cancer metastasis." (PMID 37996892, 2023). "In the present commentary, we discuss new observations stating that angiopoietin-like protein 1 (ANGPTL1) attenuates cancer metastasis and stemness through Forkhead box O-3a (Foxo3a)–SRY-related HMG-box-2 (Sox2) axis in colorectal cancer (Clin." (PMID 36156125, 2022). "Among these m6A regulators, IGF2BP2 had been proven to be a downstream m6A reader of SOX2 in colorectal carcinoma." (PMID 35558067, 2022). "proved that METTL3 upregulates SOX2 expression through IGF2BP2 to recognize and increase the stability of SOX2 mRNA and promote colorectal carcinoma cell self-renewal, increase stem cell frequency and promote migration in a m6A-dependent manner." (PMID 35299748, 2022). "Higher expression of IL20RA and SOX2 was also found in colorectal cancer tissues compared with matched para-carcinoma or normal tissues." (PMID 33456560, 2021). "This work suggests that lncRNA FENDRR can block the CSC-like traits in colorectal cancer cells through directly interacting with Sox2 mRNA 3’UTR." (PMID 34697986, 2021). "In this study, we investigated the induction and regulatory role of SOX2 in colorectal CSCs following radiation exposure in both radioresistant and radiosensitive colorectal cancer cell lines." (PMID 33445526, 2021). "METTL3 regulates colorectal cancer metastasis by enhancing the mRNA stability of SOX2, HK2 and SLC2A1 (GLUT1) through an m6A-IGF2BP2/3-dependent mechanism." (PMID 34094960, 2021). "Collectively, these results suggested that radiation enhanced PI3K/AKT/SOX2 axis promoted the induction of colorectal CSCs in radioresistant colorectal cancer cells." (PMID 33445526, 2021). "At last, we demonstrated that lncRNA FENDRR conferred the CSC-like traits and chemoresistance of colorectal cancer cells dependent on Sox2 expression." (PMID 34697986, 2021). "In this study, we investigated the induction and regulatory role of SOX2 following the irradiation of radioresistant and radiosensitive colorectal cancer cells." (PMID 33445526, 2021). "The properties of CSCs, including spheroid-like growth and metastatic potential, were observed in SOX2-positive colorectal cancer with an increased expression of CSC markers such as CD44." (PMID 33445526, 2021). "The stemness and growth properties of colorectal cancer cells are influenced by a reciprocal feedback loop involving miR-200c and the homeodomain transcription factor SOX2, with miR-200c targeting the SOX2 mRNA, and SOX2 repressing the miR-200c promoter." (PMID 34884985, 2021). "Recent studies have shown that SOX2 expression plays an important role in the maintenance of CSC properties in colorectal cancer." (PMID 33445526, 2021). "More importantly, we found that the expression of USP38 was negatively correlated with the expression of CD133, CD44, and SOX2 suggesting that USP38 negatively regulates cancer stem cells in colorectal cancer patients." (PMID 32404892, 2020). "A study in colorectal carcinoma showed that higher expression of METTL3 promotes m6A levels in SOX2 transcripts." (PMID 33228740, 2020). "The significance of SOX2 in lymph node metastasis and distant metastasis has been previously evaluated and shown that higher expression of SOX2 is correlated with lymph node metastasis, distant metastasis and poorer prognosis of colorectal cancer." (PMID 31244283, 2019). "In another study, it was reported that conditioned media derived-MSCs culture includes IL-6 able to induce expression of Oct4 and Sox2 as pluripotent markers in colorectal cancer stem cells (CSCs)." (PMID 31009502, 2019).
colorectal cancer (continued). "In the case of three colorectal cancer cell lines, growth inhibition was observed during the initial five days when SOX2 was elevated." (PMID 28388544, 2017). "Sox2 (Sry-box2) is essential for a variety of stem cells and is also expressed in colorectal cancer (CRC)." (PMID 29228716, 2017). "In the case of colorectal cancer, miR-200c, miR-638, miR-450-5p, and miR-429 have been reported to regulate SOX2, but with different outcomes." (PMID 28388544, 2017). "In colorectal cancer, introduction of a set of defined factors (Oct3/4, Sox2 and Klf4) showed an enhancement in CSC properties such as sphere formation capability, expression of CSC marker genes, chemo-drug resistance, and tumorigenicity." (PMID 26683522, 2016). "miR-429 is an oncogene, which was shown to inhibit apoptosis in colorectal cancer via SOX2 and can induce epithelial to mesenchymal transition." (PMID 27775664, 2016). "When investigating functions enriched by DEGs from SOX2 deletion in the human colorectal cancer cell line SW620 (GPA ID: GPAHSA000268), we found novel functions based on comparisons with known functional annotations from GO." (PMID 26039571, 2015). "We enriched CD133+ colorectal cancer cells which manifested the CSCs-like properties such as higher levels of other stem cell markers Oct-4 and Sox-2, tumor sphere forming ability and more tumorigenic in NOD/SCID mice." (PMID 26284927, 2015). "SOX2 drives fetal reprogramming and reversible dormancy in colorectal cancer – Vivian S.W. Li from the Francis Crick Institute, United Kingdom, presented her recent research on cellular plasticity in colorectal cancer (CRC)." (PMID 41221269, 2025). "Recently, SOX2 expression has been reported to be associated with lymph node metastasis and distant metastasis in colorectal carcinomas and is a poor prognostic factor." (PMID 40104101, 2025). "Furthermore, in colorectal cancer tissues, miR-429 overexpression, by directly targeting SOX2 in HT-2 cells, impedes cell apoptosis." (PMID 38914806, 2024). "The expression of a single transcription factor, such as OCT4 or SOX2, may make colorectal cancer cells more aggressive." (PMID 38072050, 2023). "Our previous study demonstrated the effect of SOX2 in promoting VM in colorectal cancer (CRC)." (PMID 38044399, 2023). "Finally, SOX2 knockdown in colorectal cancer SW620 cells, which withstand SOX2 loss, caused significant increase in endogenous HERVH-CALB1 expression." (PMID 37192000, 2023). "For example, Beclin1/autophagy signaling mediates Sox2-promoted chemoresistance, proliferation, stemness, migration, and invasion in colorectal cancer cells, and IL-6 activates autophagy via the IL-6/JAK2/BECN1 pathway, promoting chemotherapy resistance in colorectal cancer." (PMID 37303041, 2023). "Additionally, TM4SF1 can promote cell migration, invasion, and stemness maintenance through the Wnt/β-catenin/c-Myc/SOX2 axis in various cancer, such as colorectal cancer." (PMID 37728418, 2023). "Tests registered for in vitro diagnostics that examine the methylation of promoter regions of various genes in ctDNA (e.g., SEPT9 for colorectal cancer or SOX2 for NSCLC identification) are of limited use in CUP diagnosis due to inadequate sensitivity and low organ specificity." (PMID 35884492, 2022). "We then determined whether FENDRR inhibited the CSC-like traits of colorectal cancer cells through Sox2." (PMID 34697986, 2021). "Given the evidence that SOX2 was aberrantly expressed and involved in the maintenance of CSCs in colorectal cancer, these results indicated the possibility of a functional relationship between SOX2 expression and CD44-mediated CSC property in radioresistant cells upon radiation exposure." (PMID 33445526, 2021). "Interestingly, we also found that the radiation-induced activation of PI3K/AKT pathway functions as an upstream regulator of SOX2-dependent induction of CSCs in colorectal cancer." (PMID 33445526, 2021).
colorectal cancer (continued). "Upon irradiation, the overexpression of SOX2 facilitated the acquisition of the properties of colorectal CSCs in radiosensitive colorectal cancer cells (SW480 and LoVo) due to an increase in CD44+ population, cell survival, migration, invasion, and tumoursphere-formation." (PMID 33445526, 2021). "Our previous study has demonstrated the oncogenic role of SOX2 in colorectal cancer (CRC)." (PMID 33953166, 2021). "Another meta-analysis on colorectal cancer showed SOX2 correlation with worse survival." (PMID 34436030, 2021). "We further determined whether the expression of either CD44 or SOX2 in response to radiation is dependent on radioresistant colorectal cancer cells." (PMID 33445526, 2021). "In addition, lncRNA FENDRR-mediated effects on the CSC-like traits of colorectal cancer cells depended on Sox2 expression." (PMID 34697986, 2021). "CD133, CD44, and SOX2 are widely considered to be markers of colorectal cancer stem cells." (PMID 34573091, 2021). "Taken together, these results suggested that SOX2 regulated population growth and properties of CSCs in colorectal cancer following irradiation, and SOX2 may be a potential target for studies involving resistance to radiation." (PMID 33445526, 2021). "Sox2 was knocked down in colorectal cancer cells with FEDNRR knockdown." (PMID 34697986, 2021). "In many cancer types, such as oral squamous cell carcinoma and colorectal carcinoma both nuclear and cytoplasmic localizations of SOX2 have been previously reported while in lung squamous cell carcinoma and nasopharyngeal carcinoma nuclear localization appears to predominate." (PMID 34211078, 2021). "By analyzing both serial stains and the multiplex staining of CDX2 and SOX2 we confirmed their inverse relationship in colorectal cancer; however, the inverse correlation was considerably stronger for DIA (Spearman’s rho test, Allred r = −0.16; DIA r = −0.51; n = 357)." (PMID 31641225, 2020). "Furthermore, a positive correlation between PIWIL2 and the undifferentiated cell marker SOX2 have been observed in colorectal cancer tissues." (PMID 31443431, 2019). "Colorectal cancer tissue samples also expressed the Sox2 protein at moderate levels." (PMID 30518951, 2018). "Recent studies have explored the potential prognostic value of a set of colorectal cancer stem cell markers—CD133, LGR5, ALDH1, CD44v6 and SOX2—investigated alone or in association with immune-related cell markers—CD3, CD8, Foxp3 and PD-L1—in 104 stage III colorectal cancer patients." (PMID 29652830, 2018). "However, this is inconsistent with the apparent oncogenic role of SOX2 in a subgroup of colorectal cancer patients." (PMID 28388544, 2017). "SOX2 is a transcription factor essential for maintaining pluripotency, but its ectopic expression may be involved with abnormal differentiation of colorectal cancer cells." (PMID 25333365, 2014). "Our results indicated that Sox2 overexpression induced autophagy in HCT116 colorectal cancer cells." (PMID 23451179, 2013). "Finally, an IHC analysis of 44 cases of colorectal cancer patients suggested that SOX2 is a prognosis marker for metastasis of colorectal cancers." (PMID 22912670, 2012). "In addition, we provided a link between SOX2 activity and the WNT pathway by showing that knock down of SOX2 reduced the WNT pathway activity in colorectal cancer (CRC) cells." (PMID 22912670, 2012). "We stained SOX2 knock down and MOCK knock down colorectal cancer cells with ß-catenin antibody and found that there is an accumulation of ß-catenin in the cell membrane relative to cytoplasm and nucleus in the SOX2 knocked-down cells compared to the MOCK control." (PMID 22912670, 2012). "However, paradoxical upregulation of Sox2 influenced spheroid formation under GF-supplemented conditions, suggesting that Sox2 may contribute to drug resistance or recurrence in colorectal cancers." (PMID 42065072, 2026).
colorectal cancer (continued). "The oncogenic role of long non-coding RNA SOX2 overlapping transcript (SOX2-OT) has been demonstrated as a miRNA decay system that sponges tumor suppressor miRNA, including miR-122-3p in glioblastoma and miR-194-5p in glioblastoma, gastric, and colorectal cancers." (PMID 37524903, 2023). "In addition, it was demonstrated that SOX2 plays a crucial role in colorectal CSCs and that SOX2 may play a role in the tumour progression and recurrence in colorectal cancer." (PMID 36614288, 2023). "In our previous study, methyltransferase‐like 3 (METTL3) facilitated colorectal carcinoma (CRC) progression through increasing SOX2 expression to maintain the CRC stemness phenotype in an m6A‐IGF2BP2‐dependent machinery." (PMID 38082402, 2023). "SOX2 protein may serve as a novel prognostic factor for colorectal cancer." (PMID 33425489, 2021). "Therefore, this is an interesting finding that radiation-activated PI3K/AKT pathway genes were essential for the SOX2-dependent induction of colorectal CSCs, and it is potentially an effective therapeutic target for CSCs in colorectal cancer activated by radiation." (PMID 33445526, 2021). "In view of our earlier proposal that SOX2 levels must be carefully titrated to maximize tumor growth, one of the mechanisms by which miR-429 promotes colorectal cancer may be to help maintain SOX2 within optimal levels for the BRAFV600E mutant subgroup of colorectal tumors." (PMID 28388544, 2017). "In addition, we also found that SOX2 expression in primary human colorectal cancer tissues could predict tumor metastasis in human CRC patients." (PMID 22912670, 2012). "Finally, our data suggested that SOX2 could be used as a marker to predict liver/lymph node metastasis in colorectal cancer patients." (PMID 22912670, 2012). "In summary, we demonstrated that silencing SOX2 could induce a mesenchymal-epithelial transition in colorectal cancer cells, which partially explain the observation that SOX2 knock down lowered cell mobility and invasion ability in vitro and reduce metastasis in vivo." (PMID 22912670, 2012). "In other malignancies, such as colorectal cancer (CRC) and small cell lung cancer (SCLC), SOX2 often correlates with worse survival, chiefly through its roles in promoting stemness, chemoresistance, and EMT." (PMID 40227667, 2025). "In colorectal cancer, METTL3 promotes the stability of SOX2 mRNA by catalyzing its m6A modification, thereby promoting tumor development." (PMID 40003919, 2025). "Employing the Wnt/β‐catenin/c‐Myc/SOX2 axis, TM4SF1 preserves the stemness and EMT of cancer cells during colorectal cancer recurrence and metastasis." (PMID 39789998, 2025). "In colorectal cancer, TM4SF1 was found to promote cell metastasis and maintain the EMT phenotype and cancer stemness via the Wnt/β‐catenin/c‐Myc/SOX2 pathway." (PMID 38494915, 2024). "In colorectal cancer, METTL3 methylates SOX2 mRNA, allowing it to bind to the mRNA-binding protein IGF2BP2 at m6A sites, preventing SOX2 mRNA degradation and promoting protein expression." (PMID 38238831, 2024). "In colorectal cancer, higher METTL3 expression in metastatic tissues was responsible for elevated SOX2 expression, which contributed to colorectal cancer cell stemness and malignancy." (PMID 38001065, 2023). "In colorectal cancer, METTL3 cooperates with IGF2BP2 to increase the stability of SOX2 RNA, which promotes the transcription of MYC and enhances the self-renewal and proliferation of tumor cells." (PMID 37996892, 2023). "The administration of AP or P or AP + P as therapy or prophylaxis in PHZ-induced colorectal cancer significantly downregulated the colonic mRNA expression of PI3K, AKT, c-Myc, CK-20, SOX-2, OCT-4, and NanoG compared to the PHZ group." (PMID 37513415, 2023). "Spheroid culture from the HT-29 cell line, a more realistic colorectal cancer in vitro model, shows significantly higher expression of ABCG2, NANOG, SOX2 and POU5F1 compared to 2D cell culture conditions." (PMID 37445716, 2023).
colorectal cancer (continued). "In colorectal carcinoma (CRC), METTL3 promotes stemness and tumor progression by regulating the expression of SOX2 through an m6A-IGF2BP2-dependent mechanism." (PMID 38012755, 2023). "Here, we integrate the possible mechanisms for ANGPTL1 inhibiting colorectal cancer liver metastasis and discuss the regulation of ANGPTL1 on the Foxo3a–Sox2 pathway." (PMID 36156125, 2022). "For example, SOX2 was shown to increase the expression of Beclin 1 and facilitate the maturation of autophagosomes, promoting the EMT and CSC properties of colorectal cancer." (PMID 36187468, 2022). "Consistently, levels of prostaglandin E2 (PGE2), one of the members of the prostanoid, correlated with cancer stem cell markers in colorectal cancer, including CD133, CD44, LRG5, and SOX2." (PMID 36494785, 2022). "For instance, TM4SF1 activates Wnt signaling and promotes the expression of SOX2 to maintain stem cell properties and EMT in colorectal cancer, facilitating metastasis and recurrence." (PMID 35653786, 2022). "Consistent with our findings, an inverse correlation between SOX2 and CDX2 was recently reported in gastric cancer and colorectal cancer, suggesting the mutual suppression of the expression of SOX2 and CDX2." (PMID 35602937, 2022). "A recent study reported that SOX2 expression primarily coincided with CD44+ and ALDH1+ population in pancreatic CSCs and CD44+ and CD24+ in colorectal cancer." (PMID 33445526, 2021). "Researches in colorectal cancer (CRC) have also shown that METTL3 upregulates in the cells and through an m6A-dependent manner and maintains the expression of SRY-box 2 (SOX2) that is a CSC marker." (PMID 34051847, 2021). "This analysis showed that CD133, CD44, and SOX2 expression and ALDH activity were slightly increased in TCCM-treated colorectal cancer cells, whereas TCCM-DPA treated cancer cells exhibited a significant decrease in the expression/activity of these proteins." (PMID 34573091, 2021). "The aim of this study was evaluation the effect of orlistat on the expression of OCT4, Nanog, SOX2, and KLF4 genes in the colorectal cancer SW40 cell line." (PMID 34452543, 2021). "We initially detected the levels of FENDRR and Sox2 in 5-Fu resistant (HT-29/5-Fu) and sensitive (HT-29) colorectal cancer cells and found that HT-29/5-Fu exhibited a lower level of FENDRR and higher level of Sox2 compared to HT-29 cells, respectively." (PMID 34697986, 2021). "We found that CCNP increases spheroid formation in breast, lung and colorectal cancers, and upregulates the expression of stemness (CD44, CD133) and pluripotency (SOX2, OCT4, NANOG) markers." (PMID 34604945, 2021). "Taken together, our results suggest that the FEDNRR/Sox2 axis suppresses the CSC-like traits and thus drug resistance in colorectal cancer cells." (PMID 34697986, 2021). "We performed DIA of fluorescence-based mIHC stains of CDX2, SOX2, SOX9, E-cadherin, and β-catenin in colorectal cancer samples arranged in TMAs, and compared with previous visually scored chromogenic IHC stains of the same series." (PMID 31641225, 2020). "SOX2 immunostaining was performed on tissue micro-arrays containing tumor cores from 797 patients with stage II and III colorectal cancer." (PMID 32365581, 2020). "We applied this method for five biomarkers (CDX2, SOX2, SOX9, E-cadherin, and β-catenin) using tissue microarrays of a Norwegian unselected series of primary colorectal cancer." (PMID 31641225, 2020). "Our group confirmed the correlation between PrPC and CSC by demonstrating that the levels of PrPC and CSC marker proteins such as Oct4, Nanog, Sox2, and ALDH1A1 significantly increased in human colorectal cancer tissues and colorectal cancer cells." (PMID 33276687, 2020). "In colorectal cancer, IGF2BP2 can recognize m6A sites in the CDS region of SOX2, enhancing its stability and preventing its degradation, leading to the occurrence and development of colorectal cancer." (PMID 33363011, 2020).